CD4 (CD4 molecule)
Diseases named in the same sentence as CD4 in open-access papers (continued):
Sharing a sentence is not in itself a finding about the gene and the disease.
diabetes (continued). "Furthermore, neutralizing antibodies to IL-10/TGF-β were administrated to evaluate the role of IL-10/TGF-β in p524-expanded CD4+CD25+ T cell-mediated prevention from diabetes transfer." (PMID 19759824, 2009). "Tim3-/- mice have exacerbated diabetes due partly to a defect in CD4+CD25+ Treg cell function." (PMID 18664279, 2008). "Additionally, regulatory T cells (Tregs) significantly increased in the liver of diabetes vs. non-diabetes (p < 0.01), while CD4+CD44+CD62L− and CD8+CD44+CD62L− effector memory T cells were increased in diabetes with NASH compared to diabetes alone (both p < 0.01)." (PMID 40362271, 2025). "Because tetramer-binding CD4 T cells reactive to either 2.5HIP or 6.9HIP were shown to accumulate in the islets as diabetes advances, the production of the 2.5HIP may also be driven by islet inflammation, as observed by the increased levels of 6.9HIP in stressed islets in the current study." (PMID 38455055, 2024). "In 2015, Łuczyński and collaborators found an increased count of circulating CD4+ T cells with the Th17 phenotype in children with obesity (10–18 years old) and suggested these cells played a key role in low-grade inflammation and established the link between obesity and diabetes." (PMID 38397455, 2024). "However, age, gender, occupation, educational status, current CD4+ count (cells/mm3), previous hospitalization and diabetes status, history of catheterizations, and urinary tract urgency had a statistically significant association with significant bacteriuria and Candidauria." (PMID 38820330, 2024). "Therefore, the present study indicated that EPE could ameliorate the incidence of type 1 diabetes mellitus and immunoregulation accompanied by a decrease in the number of CD4+ IL-17 cells and blood cytokine levels of IL-6 through the regulation of Th17 cells." (PMID 37373070, 2023). "The activation of CD4+ T cell differentiation through Th1 and Th2 cells, as well as the dysfunction of Th17 cells and T regulatory cells, which affect the balance of pro- and anti-inflammation, are all potential pathways that diabetes may follow." (PMID 36992148, 2023). "However, the results of one study revealed a positive association between the frequency of CD4+ CD28null T cells and the first cardiovascular event in patients with diabetes, but without overt CVD." (PMID 36855107, 2023). "These factors were further analyzed by multivariable logistic regression analysis and the results indicated that uncontrolled diabetes, platelet < 40 × 109/L, CD4+ T cell < 300/μL and CD8+ T cell < 400/μL could be recognized as independent predictors for IPA in SFTS patients." (PMID 36707667, 2023). "Analogously to the association of markers of diabetes with diabetic nephropathy, the absolute CD4 count at the time of biopsy may not reflect counts during the first years of infection, when renal injury may have occurred." (PMID 35430806, 2022). "Some studies also did not reveal an association between CD4 levels and diabetes." (PMID 36733932, 2022). "Diabetes mellitus (p = 0.0076), serum albumin level (p = 0.030), Eastern Cooperative Oncology Group Performance Status (ECOG PS) (p = 0.0007), serum CA19–9 level (p = 0.0028), and peripheral CD4+ T cell ratio (p = 0.011) were significantly associated with prognosis in multivariate analyses." (PMID 36333670, 2022). "Transfer of diabetogenic CD4+ T-cells did not cause diabetes in NOD.α4-/- mice." (PMID 33291571, 2020). "People with all forms of diabetes are at increased risk due to defective innate immunity as well as adaptive immunity Severe Covid-19 infection significantly reduces the numbers of natural killer cells, notably CD4+ and CD8+ cells, as well as CD4+ as CD8+ lymphocytes." (PMID 33133024, 2020).
diabetes (continued). "Some of the predisposing factors that have been identified include: dose and duration of treatment, low CD4 count, advanced age and low body weight, co-prescription of didanosine or boosted protease inhibitor, pre-existing chronic kidney disease (CKD) and associated diabetes mellitus." (PMID 28904656, 2017). "However, it has been observed that the transfer of diabetes is delayed by treatment of recipients mice by anti-class II monoclonal Abs, indicating that interactions between CD4+ effector T-cells and APCs through class II-mediated antigen presentation is still required for efficient transfer." (PMID 28424681, 2017). "To test this assumption, we performed adoptive transfers of effector CD4+CD62L T cells together with CD11b+ bone marrow cells from HDC-deficient or WT mice to NOD RAG−/− recipients, which did not alter diabetes onset, ruling out the increase of IMCs as a cause for diabetes progression." (PMID 26090474, 2015). "Therapeutic modalities directed at improving CD4 activation may prevent the initial loss of tolerance; however, CD8 specific therapies may be particularly advantageous in obviating the cell mediated destruction that characterizes diabetes progression." (PMID 25171173, 2014). "There was no significant enrichment for genomic regions associated with control conditions (ones in which CD4+ cells would not be expected to play a dominant role), such as coronary heart disease, atopic dermatitis and type 2 diabetes mellitus (P>0.05 for all)." (PMID 23849224, 2013). "Of importance, we hypothesized and subsequently confirmed experimentally that the epitope (GAD570–585, p570), which displayed similar characteristics to p524, was a protective epitope by showing that p570-expanded CD4+CD25+ T cells suppressed the onset of diabetes in NOD mice." (PMID 19759824, 2009). "These 8.3-CD8+ T effector cells were consistently present in NOD islets, and with the help of CD4+ T cells, they transfer diabetes into NOD.Scid mice, and accelerate diabetes onset when highly expressed in NOD mice (8.3-NOD transgenic mice)." (PMID 41596443, 2026). "Treg cells are a subset of CD4+ T cells that express IL-2 receptor alpha chain CD25 and FOXP3 transcription factor to maintain immune tolerance during diabetes." (PMID 41948347, 2026). "Low-dose IL-2 significantly expanded CD4+CD25+Foxp3+ Tregs in the blood and spleen of mouse models of OIR and diabetes (1.4- to 1.9-fold increase, p<0.01)." (PMID 40133487, 2025). "In conclusion, this review identified an increase in monocytes/macrophages, neutrophils, and CD4+ and CD8+ T cells and a reduction in iNKT cells in the liver of individuals and animals with diabetes." (PMID 40362271, 2025). "The model incorporated predictors identified through multivariate logistic regression, including smoking status, CMV infection, diabetes, NLR, LDH, PFR, and CD4 + T cell." (PMID 40382550, 2025). "In this model, antigen-specific CD4+ T cells, which recognize a peptide expressed on pancreatic beta cells, were transferred from BDC2.5 transgenic mice into NOD-SCID mice to induce diabetes." (PMID 40585231, 2025). "Specifically, patients with diabetes mellitus undergoing HD for half a year displayed an increase in CD3+CD8+, natural killer cells, CD4+CD28 null, and CD8+CD28 null." (PMID 41226416, 2025). "Iron deficiency affects the functions of T regulatory (Treg) cells and natural killer (NK) cells, while diabetes more strongly affects the function of CD8+ and CD4+ cells (Th1 and Th2)." (PMID 40429402, 2025). "Variables included age, gender, CD4 count, body mass index, ART regimen and duration, and family history of diabetes." (PMID 41399597, 2025). "At baseline, 147 people treated with FTC/TAF/BIC had a better lipid profile and lower CD4 cell count than 147 people treated with 3TC/TDF/DOR; diabetes was less frequent in the latter group." (PMID 41050592, 2025). "This review underscores the increased proportion of activated CD4+ and CD8+ T cells in the liver in diabetes." (PMID 40362271, 2025).
diabetes (continued). "In contrast, CD4+(CD44−CD62L+) (p < 0.001) and CD8+(CD44−CD62L+) (p < 0.01) intrahepatic naïve T cells were lower in diabetes with NASH." (PMID 40362271, 2025). "In this adoptive transfer model, CD4+ T cells specific for a beta cell antigen were transferred from BDC2.5 transgenic mice to NOD-scid mice, inducing diabetes." (PMID 40585231, 2025). "Significant abnormalities in the CD4+ T lymphocyte count and CD4+/CD8+ ratio in patients with diabetes combined with pulmonary infection have been reported in the literature." (PMID 40109771, 2025). "These variables included smoking status, dyspnea, diabetes, NLR, LDH, PFR, CD4+ T cell, adjunctive corticosteroid use, and CMV infection." (PMID 40382550, 2025). "We transferred BDC2.5/CTRLKO or BDC2.5/PD‐1KO CD4+ T cells together with 8.3 cells into NOD mice and monitored them for diabetes." (PMID 40623940, 2025). "Main prognostic factors of mortality included elderly, diabetes mellitus, HIV with low CD4 (<200 μL/cells), late symptomatology, infection involving the abdominal wall, and high Fournier’s gangrene severity score (>9)." (PMID 39840205, 2024). "We found that individuals with diabetes had elevated anti-SARS-CoV-2 IgG levels and greater proliferative CD4 + T-cell responses." (PMID 38642547, 2024). "For example, T cells, particularly CD4+ helper T cells and CD8+ cytotoxic T cells, are key mediators of vascular inflammation in diabetes." (PMID 38809515, 2024). "Tr1 cells, likely arising from memory and total CD4 T-cells, controlled effector T-cells via IL10 signaling to limit the development of diabetes." (PMID 38543910, 2024). "In diabetes, MLL1 and Notch-receptor signaling was upregulated in wound CD4+ Th cells, driving CD4+ T cells toward the Th17 cell phenotype." (PMID 39250432, 2024). "In NOD mice with a selective modification of iPLA2β in only the T cells, CD4+ and CD8+ T cells were purified from pre-diabetic NOD and NOD.HET spleens and were administered to NOD.scid mice, in a ratio known to induce diabetes." (PMID 39359722, 2024). "On the other hand, the pathophysiology of type 1 diabetes mellitus (T1DM), which accounts for 10% of all cases of diabetes, classically involves the autoimmune destruction of β-cells in the pancreas by invading CD4+ and CD8+ T-cells and macrophages." (PMID 38338796, 2024). "With a median follow-up in excess of 5 years, we found no short-term risk of ALT elevation with the use of INSTIs, even after adjusting for confounders including viral hepatitis, BMI, CD4 cell counts, HIV-RNA, dyslipidemia, and diabetes mellitus." (PMID 38919512, 2024). "To assess the functional aspects of cytotoxic T cells, we calculated the cytotoxicity score for CD4 Tcyt and CD8 Tem using cytotoxic genes (PRF1, GZMH, and GZMK) and observed higher cytotoxicity scores in T2D patients compared to non-diabetes." (PMID 39072276, 2024). "The upregulation of CD73 with agents, including AGT-5, Aire-overexpressing DCs, Aspirin, BAFFR-Fc, CD4+ peptide, ICAs, IL-2 therapies, SAgAs, sCD73, stem cells, RAD51 inhibitor, TLR9 inhibitor, and VD, decreased diabetes and atherosclerosis development." (PMID 39735551, 2024). "In the current study, the cytotoxic scores of CD4 Tcyt cells, CD8 Tem cells, and γδ T cells were higher in T2D patients than in the non-diabetes." (PMID 39072276, 2024). "Overexpressing CD73 with agents, such as AGT-5, Aire-overexpressing DCs, BAFFR-Fc, CD4+ peptide, ICAs, IL-2 therapies, SAgAs, sCD73, RAD51 inhibitor, TLR9 inhibitor, and VD decreases diabetes development." (PMID 39735551, 2024). "Notably, NOD mice genetically engineered for deficiency of mature B cells do not develop diabetes, and this lack of disease progression is associated with dramatic reductions in islet antigen-specific CD4+ and CD8+ T cells in secondary lymphoid organs and insulitic lesions." (PMID 38515750, 2024).
diabetes (continued). "These in vitro findings were confirmed in vivo, using CD4+/CD25− T lymphocytes from NOD BDC2.5 mice that, upon inoculation into NOD.SCID mice, promote the appearance of diabetes within less than 10 days." (PMID 38967669, 2024). "NOD-PD-1-/- mice developed diabetes much earlier than in NOD-PD-1+/+ mice with early insulitis and increased infiltration of CD4+ and CD8+ T cells." (PMID 37342323, 2023). "Impaired tissue migration of CD4+ and CD8+ effector memory and TEMRA cells, however, have been reported among diabetes patients suggesting the sequestration of these cells in the peripheral circulation." (PMID 36333945, 2023). "CD4+ and CD8+ T cell enrichment in target tissues was observed in irAEs leading to diabetes, colitis, and thyroiditis." (PMID 37342323, 2023). "Van Belle found that NKG2D expression was increased on CD4+ and CD8+ T cells in virus-induced diabetes and that when NKG2D was blocked with an antibody, it failed to reverse the recent onset of diabetes in NOD mice." (PMID 38139373, 2023). "Many subsets of Tfh cells, such as CXCR5+ PD1+ ICOS+ and CD4+ CXCR5+ PD-1+, are increased in children and adults with diabetes." (PMID 36776877, 2023). "In other mouse models of autoimmune diseases, such as C57BL/6 mice, CD4+ CD25+ Tregs are also induced by recombinant IL-2, thus preventing the progression of diabetes." (PMID 36776877, 2023). "Collectively, these results indicate that there are more circulating CGC+ CD4+ and CGC+ CD8+ T cells in persons with HIV with subclinical atherosclerosis, NAFLD, pre-diabetes, and diabetes." (PMID 36865544, 2023). "Cases with myocardial infarction, stroke, sudden death, or diabetes after starting antiretroviral therapy were included with the available samples and controls matched for sex, age, tobacco use, pre-ART CD4 cell count, viral load, and sample time-point." (PMID 37512990, 2023). "While circulating CGC+ CD8+ and CGC+ CD4+ T cells were strongly correlated, they differed in their relationships with CAC, NAFLD, diabetes, and pericardial fat volume." (PMID 36865544, 2023). "We observed that conventional CD4+ T cells, albeit presumably tolerant to OVA, increased the incidence of experimental diabetes and accelerated its onset." (PMID 36705564, 2023). "In case–control studies, patients with diabetes had higher blood levels of CD4+CD28− and CD4+ & CD8+ T effector memory RA+ (TEMRA) cells compared to those without diabetes." (PMID 36333945, 2023). "This suggests that the interaction between diabetes and HIV exacerbates the depletion of CD4+ T cells seen in HIV infected subjects." (PMID 37545969, 2023). "In this model, co-transfer of naïve CD8+ OT-I and activated CD4+ OT-II T cells, each with a specificity for OVA, into RIP-OVAhi mice that express islet-specific OVA antigen, induces rapid diabetes development." (PMID 35563015, 2022). "We next wanted to dissect the separate roles of HPSE-1 in antigen-specific CD4+ and CD8+ T cells in the process of islet infiltration and diabetes pathogenesis." (PMID 35563015, 2022). "These mice developed diabetes when injected with polyI:C (Toll-like receptor 3 agonist) and spontaneous diabetes when co-expressing RIP-hB7.1 along with CD8+ and CD4+ T cell responses that largely overlap." (PMID 35498419, 2022). "It was found that the response ability of CD4+ T cells producing IFN-γ and TNF-α was negatively correlated with the severity of diabetes." (PMID 35692502, 2022). "We evaluated some factors correlated with sofosbuvir-daclatasvir treatment failure: gender, diabetes mellitus, previous IFN failure, cirrhosis, concomitant ribavirin use, high baseline HCV-RNA, and low CD4 cell count." (PMID 34383853, 2021). "In an additional comparison between PJP− and PJP+ patients with similar treatment and diabetes status among the MDA5+ DM patients, PJP occurred at a median of 2 months and at the time of a clear decrease of CD4+ T cell count and lymphocyte count." (PMID 34481528, 2021).
diabetes (continued). "About 4% had comorbid diabetes (n = 477), and 6% had comorbid HIV (n = 677); among whom baseline CD4 count was <350 cells/mL in 23% (n = 156), 350 to 499 cells/mL in 23% (n = 155), ≥500 cells/mL in 52% (n = 355), and missing in 2% (n = 11)." (PMID 34543267, 2021). "After the adoptive transfer of activated CD4+ T cells specific for the I-Ab-restricted LCMV GP61–80 epitope (Smarta), RIP-GP mice with a polyclonal CD8 TCR repertoire developed diabetes with a 20% onset rate." (PMID 33923792, 2021). "Smoking, hypertension and diabetes were the leading factors contributory to CVD among PLWH, HBV and HCV infection to ESLD, and declined eGFR level, low CD4 cell count at initiation of ART, and diabetes to ARD." (PMID 33620297, 2021). "BpOmpW re-exposure in insulin-resistant mice maintained an activated T-cell status and high IFN-γ recall responses from CD4, CD8, and NKT cells, which would be essential to protect people with diabetes from melioidosis." (PMID 34966388, 2021). "Although 4.1-NOD and 4.1-NOD.Rag2−/− mice spontaneously develop a highly accelerated form of diabetes, the bulk 4.1-CD4+ population of these animals is hypo-responsive to TCR stimulation as compared to bulk CD4+ T cells from NOD mice." (PMID 34527002, 2021). "Our results demonstrated diabetes augments Th1 and Th17 response in EAMG rats, which is in line with previous observations that CD4+ T-cell-derived IFN‐γ and IL-17 were increased in diabetic settings both in human and animal models." (PMID 34702288, 2021). "NLRP3 inflammasome hyperactivation in diabetes, pyroptosis, and low-grade inflammation lead to a delay of INF-γ response and lower CD4+ and CD8+ cell numbers." (PMID 33329516, 2020). "CD4+ T-cell depletion lowers the incidence of T1DM in NOD mice, and even overt diabetes, suggesting its primary role in the development of T1DM." (PMID 32802890, 2020). "Factors such as depression, diabetes, substance abuse, HCV viral load >6MM IU/ML, FIB-4 score >3.25, CD4 count <200 cells/mm3, and DAA plus ribavirin therapy were independently associated with not achieving SVR12." (PMID 32053682, 2020). "In NOD mouse model, both CD4+ T-cells and CD8+ T-cells are transferred from donors to induce diabetes." (PMID 32802890, 2020). "In contrast, approximately 80% of the NOD-HET remained diabetes free, and this was accompanied by reduced iPLA2β (~65%) and TNF-α production by CD4+ T cells and higher M2 marker, Arg1, relative to NOD." (PMID 32814707, 2020). "One multicenter cohort study also included diabetes mellitus, hydrocephalus, and vasculitis as prognostic factors (HAMSI scale), and one category included HIV patients with low CD4 counts." (PMID 30611205, 2019). "On multivariable analysis, a CD4+ cell count <200 cells/μL (AHR 27.30, CI 2.40–310.27, p = 0.008), male gender, S. aureus nasal carriage, and diabetes were found to be independent predictors of S. aureus peritonitis." (PMID 30991864, 2019). "In the case of children with diabetes, positive for complement fixing islet cell antibodies (CF-ICA), there was a consistent increase in the CD8/CD4 lymphocyte ratio before the clinical onset of the T1D66." (PMID 30733517, 2019). "This study findings further demonstrated limited use of malaria RDTs, blood pressure, diabetes, and dyslipidaemia assays, low testing of HBV, and low repeated CD4 testing due to test stock-outs." (PMID 31340833, 2019). "In this model of diabetes transfer, CLI-095 decreased the activation of CD4+ T lymphocytes and the secretion of pro-inflammatory cytokines." (PMID 31852918, 2019). "Other predictors of MDRTB mortality include drug resistance pattern, diabetes history, anemia, positive sputum smear, hepatitis and drug use, resistance to ofloxacin, HIV positive infection, and low CD4 count." (PMID 30891315, 2019). "The remaining 4 studies reported as follows: limited used of malaria RDTs, limited used of blood pressure, diabetes, and dyslipidaemia assays, low testing of HBV, and low repeated CD4 testing." (PMID 31340833, 2019).